BCL6 (BCL6 transcription repressor)
Diseases named in the same sentence as BCL6 in open-access papers (continued):
Sharing a sentence is not in itself a finding about the gene and the disease.
lymphoma (continued). "Double-expressor lymphoma and double-expressor with positive Bcl6 staining were observed in 9 (21%) and 8 (19%) patients, respectively, and all of whom were found in non-GCB subtype." (PMID 31189479, 2019). "FBXO11 has been found to target BCL6 for ubiquitin-mediated degradation and mutations in FBXO11 associated with lymphoma." (PMID 31042473, 2019). "Although EZH2, MYC, BCL2 and BCL6 are important prognostic biomarkers for lymphomas, our study shows that they poorly influence the sensitivity of lymphoma cell lines to DZNep-mediated apoptosis." (PMID 31419226, 2019). "Five patients carried all the three rearrangements, so called “triple hit lymphoma” (THL – MYC+/BCL2+/BCL6+) and for survival analysis were considered among DHLs." (PMID 31976479, 2019). "The BCL6 transcription factor plays a central role in establishing the GC phenotype in B cells, and most lymphomas are dependent on BCL6 to maintain survival, proliferation, and perhaps immune evasion." (PMID 30874354, 2019). "In the 2016 WHO classification, this category has been eliminated and replaced by the category “high-grade B cell lymphoma, with MYC and BCL-2 and/or BCL-6 rearrangements”, which encompasses “double” and “triple-hit” lymphomas." (PMID 31115699, 2019). "For example, Bcl6 and Bcl11a, which are marker genes for lymphoma, showed higher gene expression levels in ES cells, even though located in B compartment in ES cells." (PMID 30894186, 2019). "Among the 51 cases with MYC/BCL2 co-expression, 14 cases showed concurrence of MYC, BCL2 and/or BCL6 genetic abnormalities, and the remaining 37 cases were classified as double-expressor lymphoma (DEL)." (PMID 31315646, 2019). "In a word, mounting evidence showed that BCL6 played an important role in the occurrence and development of GC-derived lymphoma." (PMID 31063496, 2019). "In particular, this includes BCL6, a transcription factor central to the GC reaction as well as an established oncogene in GC-derived lymphoma." (PMID 31586074, 2019). "Genetic translocations on the chromosome structure deregulate B Cell CLL/Lymphoma 6 (Bcl6) gene in germinal-center response in mice giving rise to different types of lymphoma." (PMID 30894186, 2019). "Overall our data show a potential role for romidepsin and JQ1 combination for the treatment of aggressive and BCL6 expressing lymphomas." (PMID 31712669, 2019). "High-grade B-cell lymphoma, with MYC and BCL2 and/or BCL6 translocations (so called “double-hit” or “triple-hit” lymphomas in the WHO 2008) often show complex karyotypes." (PMID 30696948, 2019). "The antibody recognizing various epitopes of BCL6 offers the possible opportunities for mechanism study and clinical application of lymphomas." (PMID 31063496, 2019). "Correlation between the lymphoma type, EZH2 mutation status, MYC, BCL2 and BCL6 rearrangements and DZNep sensitivity." (PMID 31419226, 2019). "Except for lymphomas, BCL6 also expresses high level in several cancer tissues, such as breast cancer, gastric cancer, ovarian cancer, non-small-cell lung cancer, and glioblastoma." (PMID 30420967, 2018). "Seven of the 13 lymphomas expressed Bcl6, the master regulator of the GC B cell program, and 11/13 were double-positive for the GC B-cell markers GL7 and Fas." (PMID 29662618, 2018). "Expression of the several STAT3-controlled mediators of lymphoma cell proliferation and survival, including Bcl2l1, Bcl6, Casp3, Ccnd3, and Myc, was reduced." (PMID 29433938, 2018). "As a human protooncogene, BCL6 was originally found in malignant lymphomas which acted as a regulator of the development and growth of B-lymphocyte." (PMID 30420967, 2018). "Unexpectedly, the B-cell tumors that developed in the transplanted mice mostly had a GC B-cell phenotype, with expression of the GC B-cell markers Fas and GL7 by nearly all lymphomas, and Bcl6 and PNA each by about half of the cases." (PMID 29662618, 2018).
lymphoma (continued). "Another piece of evidence of the implication of GFI1B reduction in lymphoma comes from its relation with B-cell lymphoma 6 (BCL6), a gene frequently expressed in T- and B-cell lymphomas." (PMID 28401061, 2017). "The combination of MYC translocation with translocations of BCL2 and BCL6 can also occur, defining the triple-hit lymphomas (THL)." (PMID 28061782, 2017). "Double-hit lymphomas, as well as their counterparts over-expressing Bcl-6, have a particularly poor prognosis, and respond poorly to standard and investigational therapies." (PMID 28416758, 2017). "Since Bcl-6 is the most frequently involved oncogene in diffuse large B cell lymphoma, the Bcl-6 inhibitor 79-6 was developed to suppress lymphoma cell growth." (PMID 27880939, 2017). "The current development of Bcl6 small-molecular inhibitor indicates a huge potential for Bcl6 as a therapeutic target to treat human lymphomas." (PMID 28738086, 2017). "Immunohistochemical analysis revealed heterogeneous expression of BCL6, including cases that were below the detection level by immunohistochemistry (IHC), as previously observed in Iμ-BCL6-derived lymphomas." (PMID 27799148, 2016). "In contrast, in another study, MYC/BCL6 (n = 13) showed significantly worse survival than MYC/BCL2 DHL (n = 20) after exclusion of triple-hit lymphoma." (PMID 26573234, 2016). "Since BCL6 expression is almost completely restricted to germinal center cells and some lymphomas, BCL6 is an attractive target for therapy with several specific BCL6 inhibitors currently being investigated." (PMID 26910115, 2016). "The biochemical study of BCL6-mediated gene repression has provided the basis for the design of agents that inhibit BCL6 and kill lymphoma cells." (PMID 27815824, 2016). "In particular, in one lymphoma (833PA) it was accompanied by overexpression of Bcl6 and in the other one (800PA) by downregulation of Bcl6, indicating a molecular heterogeneity in Patz1-dependent lymphomagenesis, sometime involving BCL6 and more often BAX." (PMID 27494852, 2016). "Targeted inhibition of these BCL6 functions has emerged as the basis for the rational design of lymphoma therapies and combinatorial regimens." (PMID 27815824, 2016). "Here we illustrated an on-target oncogene switching mechanism from BCL6 to BCL2 as drivers of the lymphoma phenotype." (PMID 26657288, 2016). "Targeting RNA by RNA interference (RNAi) or antisense oligonucleotides (ASOs) has been attempted to eradicate BCL6 from lymphoma cells." (PMID 27815824, 2016). "CBP/p300 mutant proteins found in some diffuse large B-cell lymphomas (DLBCLs) show a reduced ability to acetylate BCL6, and therefore such lymphoma cells have increased BCL6 activity, which is related to the oncogenic state of these cells." (PMID 26124919, 2015). "Biallelic deletion and silencing of FBXO11 among lymphoma cell lines occurred uniquely in FARAGE along with raised BCL6 expression." (PMID 26599546, 2015). "Members of the miR-30 family have been shown to bind to and regulate BCL6 in B-lymphocytes and lymphoma cells." (PMID 25723320, 2015). "One hundred seventy-two cases (84 %) were classified as MYC−, 17 (8 %) were MYC+/BCL2−/BCL6−, and 16 (8 %) were double/triple-hit lymphomas (i.e. MYC+/BCL2+, MYC+/BCL6+ or MYC+/BCL2+/BCL6+)." (PMID 26146524, 2015). "A proportion (21–83%) of DLBCLs with MYC translocation also harbour a BCL2 and/or BCL6 translocation, known as ‘double‐hit’ or ‘triple‐hit’ lymphoma." (PMID 27347428, 2015). "We transduced WT and mutant MEF2B-V5 into the DoHH2 DLBCL cell line and assessed expression of BCL6, a lymphoma oncogene regulated by MEF2B2." (PMID 26245647, 2015).
lymphoma (continued). "This is supported by the finding that mice with constitutive B-cell expression of BCL6 develop lymphomas similar to human DLBCL." (PMID 24595451, 2014). "Recent reports show that double hit lymphomas involving the BCL6 locus often lack CD10 expression but are GCB-like by immunohistochemistry according the Hans' algorithm, although ABC-like cases have been reported by gene expression profiling." (PMID 25349747, 2014). "Compared to MYC+/BCL2+DHL, BCL6+/MYC+DHL are less common, and most represent BCL2+/BCL6+/MYC+ triple-hit lymphomas." (PMID 24893165, 2014). "We used data related to MYC and BCL6 based on availability of datasets and based on their central role as proto-oncogene B-cell leukaemias and lymphomas." (PMID 24511376, 2013). "In primary PMBL samples pSTAT6 is only expressed in a sub-population of lymphoma cells in a pattern that is reminiscent of that of the BCL6 oncogene." (PMID 23852366, 2013). "A key oncogenic target of Bcl6-mediated repression in lymphomas is blimp-1, and the two proteins antagonise each other's expression to regulate lymphocyte differentiation [reviewed in 68]." (PMID 23874226, 2013). "The biological roles of BCL6 in normal B cell development and lymphoma oncogenesis have been intensively studied by the identification of the full set of genes that are targets of its transcriptional regulatory function." (PMID 22929622, 2012). "These IC50 values are comparable to the published data in breast cancer and Jak2/MPL mutant cells (~100 nM), but significantly less than Bcl-6-dependent lymphoma cells ( > 1 μM)." (PMID 20977755, 2010). "Since then, RhoH has been implicated in human cancer as the gene is subject to somatic hypermutation and by the detection of RHOH as a translocation partner for LAZ3/BCL6 or other genes in human lymphomas." (PMID 18823547, 2008). "Highly discriminative expression profiles were produced on both simulated gene expression data and expression data from breast cancer and lymphoma datasets on the basis of ER and BCL-6 expression, respectively." (PMID 17963508, 2007). "Resveratrol as a BCL6 inhibitor, strongly inhibits the proliferation of lymphoma cells." (PMID 39815148, 2025). "Additionally, besides being highly expressed in lymphomas, BCL6 is also highly expressed in various solid tumors such as breast cancer, ovarian cancer, and glioma." (PMID 39815148, 2025). "It highlights vital diagnostic tools, including CD45, B/T-cell markers, germinal center markers, and the Hans algorithm, as well as the role of FISH in identifying rearrangements of key genes MYC, BCL2, and BCL6, which are significant for recognizing double-hit and triple-hit lymphomas." (PMID 40428800, 2025). "In addition to MYC gene translocations, lymphomas with BCL2 or BCL6 translocations and lymphomas with both MYC, BCL2, and BCL6 translocations are known as double-hit (DHL) or triple-hit (THL) lymphomas, respectively." (PMID 40729218, 2025). "c-MYC repression across six lymphoma cell lines correlated with BCL6 levels." (PMID 40166243, 2025). "Nevertheless, all TCIPs were highly toxic to BCL6-driven lymphomas." (PMID 40166243, 2025). "Therefore, performing FISH for MYC, BCL2, and BCL6 rearrangements is essential to differentiate DH or TH lymphomas." (PMID 40428800, 2025). "Future research should aim to elucidate the subtype-specific regulatory mechanisms of MTA3 across lymphoma entities, characterize the molecular basis of its interaction with BCL6, and evaluate the therapeutic potential of targeting the MTA3-BCL6 axis in precision oncology approaches." (PMID 41584603, 2025). "A high proliferative index represented by Ki67 positivity favored a high-grade B-cell lymphoma with MYC, BCL2, and BCL6 rearrangement, possibly a double-expressor phenotype or a triple hit lymphoma if proven by classic cytogenetics, FISH, or other molecular or genetic tests." (PMID 40027040, 2025).
lymphoma (continued). "In addition, there is the term “dual or double expressor” lymphoma (DEL) that refers to MYC/BCL2 or MYC/BCL6 protein co-expression and triple expressor lymphoma (TEL) that refers to MYC/BCL2/BCL6 protein co-expression by IHC." (PMID 39038016, 2024). "Molecular subtype (GCB vs. ABC) and the presence of MYC and BCL2 or BCL6 rearrangements (as seen in double- or triple-hit lymphomas) also significantly affect outcomes, with double-hit lymphomas typically exhibiting more aggressive behavior and poorer survival rates." (PMID 39640090, 2024). "Additionally, the absence of chromosomal rearrangements commonly associated with aggressive lymphomas, such as BCL2, BCL6, and IRF4, further supported the diagnosis." (PMID 39840177, 2024). "The co-occurrence of MYC rearrangements with BCL2 and/or BCL6 rearrangements, known previously as “double-hit” or “triple-hit” lymphomas, now known as High-Grade B-Cell Lymphoma (HGBCL), is associated with very poor prognosis and resistance to conventional treatments." (PMID 40191738, 2024). "In many of these lymphomas (up to 80% in some case series), the rearrangement of MYC together with that of BCL2 and/or BCL6 has been identified, a condition defined as “double-hit” (DH) or “triple-hit” (TH) lymphomas depending on the number of pathogenetically relevant lesions identified." (PMID 38534887, 2024). "Of note, one of the 19 “double-hit” lymphoma cases showed rearrangements with all three FISH probes MYC, BCL2, and BCL6, which falls in the same diagnostic category as cases with MYC and BCL2 rearrangements only but has been called “triple-hit” lymphoma in the literature." (PMID 38903717, 2024). "Our findings demonstrate that BCL6 inhibition had anti-lymphoma activity in our DLBCL mouse model." (PMID 38485719, 2024). "Other tumor biomarkers are today commonly evaluated, including CD20, Ki-67, as well as MYC, BCL2, and BCL6, since a worst prognosis is predicted by the co-occurrence of MYC rearrangements with BCL2 and/or BCL6 rearrangements (i.e., “double-hit” and “triple-hit” lymphoma, respectively)." (PMID 38835350, 2024). "This was confirmed in a multicentre retrospective data collection study, which showed that MYC + BCL6 DH lymphoma does not represent high-risk lymphoma, while MYC + BCL2 DH lymphoma has particularly poor prognosis." (PMID 38965209, 2024). "High-grade DLBCL with MYC and BCL2 or BCL6 translocations are classified as DH/TH lymphomas." (PMID 38687198, 2024). "BCL6, functioning as a widely expressed transcriptional repressor, inhibits genes involved in cell cycle control, apoptosis, and differentiation, with selective growth suppression observed in BCL6-driven lymphoma cell lines." (PMID 39759140, 2024). "Distorted germinal centers may show residual labeling with CD10 and bcl-6, with a variable number of bcl-2+ lymphoma cells colonizing follicles." (PMID 37958219, 2023). "Double-hit or Triple-hit lymphoma (DHL/THL) is a subset of high-grade B cell lymphoma harboring rearrangements of MYC and BCL2 and/or BCL6, and usually associate with aggressive profile, while current therapies tend to provide poor clinical outcomes and eventually relapsed." (PMID 36823603, 2023). "In addition, DLBCLs were added of which approximately 15–30% have a MYC translocation, which together with BCL2 and/or BCL6 translocation or amplification are known as ‘double’ or ‘triple’-hit lymphomas." (PMID 36792656, 2023). "BCL6 targeting degraders have been well studied for lymphoma therapy." (PMID 37187757, 2023). "DLBCL with rearrangements involving MYC and BCL2/BCL6, which upregulate MYC gene expression, are referred to as double hit or triple hit lymphomas, and are associated with inferior progression free survival and overall survival in patients receiving traditional R-CHOP therapy." (PMID 36818048, 2023). "In lymphoma, BCL6 expression is sustained through different mechanisms." (PMID 38124747, 2023).
lymphoma (continued). "For example, BCL6 played a tumor-promoting role in breast cancer and most lymphomas, whereas it could act as a tumor suppressor in medulloblastoma and HB-EGF-CTF-positive GC." (PMID 37060074, 2023). "Moreover, DLBCLs harboring Myc, BLC-2, and/or BCL-6 translocations are called “double-hit” lymphoma (DHL) or “triple-hit” lymphoma (THL), which have a poor prognosis." (PMID 37483605, 2023). "The critical functions exerted by BCL6 during normal B cell development could be hijacked by malignant transformation, thereby leading to lymphoma." (PMID 35503721, 2022). "In addition, BCL6-mediated silencing of multiple target genes has been reported in primary B cells and lymphoma, where BCL6 is typically involved in maintaining cell cycle progression and controlling DNA damage-sensing and proliferation checkpoints." (PMID 36377663, 2022). "Diffuse large B-cell lymphoma (DLBCL) with MYC alteration is classified as high-grade B-cell lymphoma with MYC and BCL2 and/or BCL6 rearrangements (double/triple-hit lymphoma; DHL/THL), DLBCL with MYC rearrangement (single-hit lymphoma; SHL) and DLBCL with MYC-cluster amplification (MCAD)." (PMID 36497332, 2022). "Consequently, BCL6 inhibition suppresses lymphoma cells by simultaneously de-repressing multiple genes to deliver powerful anti-proliferation and pro-apoptotic signal to lymphoma cells." (PMID 35883106, 2022). "Consequently, we and others have sought to discover small molecule inhibitors that disrupt these interactions, aiming at identifying new treatments for BCL6-driven lymphomas, and multiple small molecule inhibitors have now been reported for BCL614–24." (PMID 36329085, 2022). "Moreover, lymphoma is more likely to invade and metastasize due to the mutation of MYD88 or BCL6 genes and the action of multiple immune cells in the tumor microenvironment." (PMID 35712495, 2022). "Furthermore, HDAC inhibitors have been reported to induce Bcl6 downregulation in GC lymphomas including DLBCL." (PMID 34926293, 2021). "BCL6 has multiple roles in normal immunity, autoimmunity, and some types of lymphoma." (PMID 34274316, 2021). "The main research of BCL6 is focused on lymphoma and it was considered as a therapeutic target." (PMID 34035992, 2021). "The most recent revision of lymphoid neoplasms by the WHO recognized a more aggressive, high-grade B-cell lymphoma subtype with a worse prognosis, the ‘double-hit’/‘triple-hit’ (DH/TH) lymphoma, which is characterized by MYC rearrangements that are associated with BCL2 and/or BCL6 rearrangements." (PMID 34207773, 2021). "Lymphomas bearing all three translocations (MYC+/BCL2+/BCL6+) are known as triple-hit lymphomas." (PMID 34372899, 2021). "The application of a multitarget BCL2/BCL6 FISH in lymphomas could improve the molecular diagnosis in terms both of time and costs." (PMID 33768318, 2021). "Also, in BCL6-driven lymphomas, inhibition of autophagy through BCL6-mediated transcriptional repression of LITAF (lipopolysaccharide (LPS)-induced TNF alpha (TNFα) factor) has been proposed to be implicated in their pathogenesis." (PMID 34782660, 2021). "Due to the particularly poor outcomes of patients with c-Myc translocation shown in some retrospective studies, these patients were reclassified as high-grade lymphoma with c-Myc translocation and bcl-2 and/or bcl-6 translocation in the 2016 WHO classification of lymphatic tumors." (PMID 32843697, 2020). "B cell lymphoma 6 (Bcl-6) is an emerging oncoprotein and therapeutic target for lymphoma." (PMID 32718354, 2020). "Furthermore, BCL6-dependency of lymphoma cell lines, including SU-DHL-4, was observed in functional CRISPR screens with BCL6 being among the most significant hits." (PMID 32180900, 2020). "BCL6 loss of function, mediated by delivery of shRNA or peptide inhibitors, can kill DLBCL cells, showing that BCL6 is necessary for lymphoma cell survival and could represent an excellent therapeutic target." (PMID 33216822, 2020).